MYC (MYC proto-oncogene, bHLH transcription factor)
Diseases named in the same sentence as MYC in open-access papers (continued):
Sharing a sentence is not in itself a finding about the gene and the disease.
lymphoma (continued). "(b) High-grade B-cell lymphoma with 11q abnormalities (HGBL-11q): This type of lymphoma exhibits morphological and immunophenotypic characteristics resembling Burkitt lymphoma, but lacks MYC rearrangements." (PMID 41561748, 2025). "The patient unfortunately succumbed to multi-organ failure secondary to acidosis, underscoring the severity of metabolic dysfunction in MYC-overexpressing lymphomas." (PMID 41180747, 2025). "The patients were divided into groups that differed in the stage of the disease, localization of the lymphoma, and in terms of rearrangements in the MYC, BCL2, and BCL6 genes." (PMID 38861004, 2025). "Nilsson Lab first demonstrated that dual inhibition of BET proteins and ATR in MYC-induced lymphoma cells triggers pronounced DNA damage, apoptosis, and senescence, both in vitro and in vivo." (PMID 41561634, 2025). "FISH testing is necessary for all large B-cell lymphomas to assess the presence of double-hit or triple-hit lymphoma (high-grade B-cell lymphoma featuring MYC and BCL2 and/or BCL6 rearrangements)." (PMID 40428800, 2025). "The EμMYC mouse model mimics the MYC translocation and spontaneously develops lymphoma in B cell lineage as early as 8–13 weeks." (PMID 39840457, 2025). "Nonsense and frameshift mutations cause a decrease in the enzyme and initiate the development of lymphoma which phenotypically mimics DLBCL or aggressive FL with overexpression of MYC and active aberrant somatic hypermutation (aSHM)." (PMID 40725159, 2025). "Overall, the genesis of lymphomas are due to typical chromosomal rearrangements, most frequently in the oncogenes MYC, BCL2, or BCL6." (PMID 40126346, 2025). "Using FISH, 23 patients had a BCL2 rearrangement, 28 BCL6, 11 MYC, and seven presented double/triple-hit lymphomas (7.7%)." (PMID 40166656, 2025). "High-risk molecular subtypes include DLBCLs with MYC and BCL2 and/or BCL6 rearrangements (“double-hit” or “triple-hit” lymphomas), now classified as high-grade B-cell lymphoma (HGBCL-DH/TH) by the World Health Organization." (PMID 41114812, 2025). "Emerging treatments such as EBV-targeted immunotherapies, immune checkpoint inhibitors, and targeted therapies against MYC and NF-κB pathways are under investigation for better management of HIV-associated lymphomas." (PMID 40496610, 2025). "These and other aspects of the MYC biology in lymphomas with a focus on DLBCL and AAs metabolism will be discussed more in depth in the subsequent chapters of this review." (PMID 41008653, 2025). "Specifically, the presence of a MYC rearrangement alongside a BCL2 rearrangement qualifies the diagnosis as double-hit lymphoma." (PMID 40428800, 2025). "Similar replication stress dependencies have been observed across diverse cancer types, including MYC-driven lymphomas, RAS-driven cancers, glioblastomas and malignant melanomas." (PMID 41561634, 2025). "In 3 disease types — pancreatic ductal adenocarcinoma, UVM, and lymphoma — the MYC pathway is activated through alternative splicing in PPP2R5A or BRD9." (PMID 40694421, 2025). "Only cells over-expressing both BCL-2 and c-MYC formed colonies in soft agar, and some eventually formed lymphomas when transplanted into mice." (PMID 40204952, 2025). "Fluorescence in situ hybridization (FISH) is a cornerstone diagnostic tool in lymphoma, serving as the gold standard for detecting specific gene rearrangements, including MYC, BCL2, and BCL6, as well as gene fusions such as IGH::MYC and IGH::BCL2." (PMID 41010038, 2025).
lymphoma (continued). "BCL6-high expressing cells SUDHL5 and K422 displayed more pronounced c-MYC repression following a 1 nM TCIP3 treatment than BCL6-low lymphoma cells OCILY19 and TOLEDO, or the leukemia line K562." (PMID 40166243, 2025). "It has also been established that this combination effectively promotes apoptosis in MYC/BCL2 co-expressing lymphoma cells and enhances T-cell responses in DLBCL." (PMID 40722681, 2025). "In cases of malignant lymphoma, chromosomal translocations have the ability to relocate super enhancers to immunoglobulin loci in close proximity to MYC, leading to an elevation in MYC expression." (PMID 39838405, 2025). "Given the transformed immunophenotype and molecular risk (MYC/BCL6, high Ki-67), aggressive combination therapy similar to other double-hit lymphomas is warranted." (PMID 41146768, 2025). "For instance, MYC translocations are characteristic of aggressive lymphoma subtypes like Burkitt lymphoma, diffused large B-cell lymphoma, and follicular lymphoma." (PMID 38326887, 2024). "High MYC expression was defined when the protein is expressed in 70% of lymphoma cells with moderate to strong staining by immunohistochemistry as such high MYC protein expression has been previously shown to identify high risk cases." (PMID 38184753, 2024). "Of interest, a recent work suggests that asparagine starvation can directly inhibit the translation of c-MYC mRNA in leukemia/lymphoma cells." (PMID 38539506, 2024). "A GCB PDX model, VFN-D7 DHL with low PTEN protein expression harbours both a BCL2 and MYC translocation, hallmarks of double hit lymphoma and the VFN-D1 KTC PDX model has wildtype PTEN protein levels, a BCL2 amplification and MYC copy number gain." (PMID 39284898, 2024). "In the revised 4th edition of the WHO Classification (2017), these lymphomas were categorized as HGBL with MYC, BCL2, and/or BCL6 rearrangements." (PMID 38914869, 2024). "Conversely, research has demonstrated that the removal of CRY2 results in an exacerbation of MYC-mediated lymphoma development in murine models." (PMID 39012661, 2024). "Additionally, investigating the c-MYC oncogene region, which co-localizes with alternate DNA structure-forming sequences in obese patients could shed light on the increased risk of developing translocation-related leukemia and lymphoma." (PMID 39043652, 2024). "The analysis of the MYC-regulated microRNAs indicated that among the four lymphoma types, HGBCL-11q showed the greatest similarity to BL." (PMID 39796140, 2024). "It represents 80–90% of DH/TH lymphoma cases, and it characterized by structural chromosomal aberrations with breakpoints at both MYC and BCL2 loci." (PMID 39684922, 2024). "c-MYC is also involved in many germinal center-derived lymphomas and the histological transformation of indolent mature B-cell malignancies (follicular lymphoma, CLL, MALT, DLBCL, BL, and PBL)." (PMID 39594704, 2024). "Recently, the WHO lymphoma classification was updated, and high-grade B-cell lymphoma with MYC and BCL2 gene rearrangements (HGBCL) was designated as its own subtype, with an inferior prognosis compared to DLBCL-NOS." (PMID 38542066, 2024). "The methylation of Sm proteins through PRMT5 has been shown to ensure splicing fidelity in MYC-driven lymphomas, where the expression of these proteins are up-regulated." (PMID 38049564, 2024). "Co-treatment of JQ1 and EZH2 inhibitor (DZNep) cooperatively inhibited MYC activation, thereby significantly restoring miR-26a expression and synergistically suppressing lymphoma growth and clonogenicity in DLBCL, BL, and MCL cells." (PMID 39580422, 2024). "Since by definition, DH/TH lymphomas require the identification of MYC rearrangement, this should be explored first, followed by BCL2 and BCL6 gene study." (PMID 39684922, 2024).
lymphoma (continued). "Most double-hit lymphomas very commonly have an inferior prognosis and are marked by MYC plus BCL2 rearrangement in about three-fourths of the cases." (PMID 39449881, 2024). "Based on these results, we presume that c-MYC is a sensor of intracellular uridine in lymphoma cells, which can be upregulated at the protein level upon treatment with lower concentrations of uridine at earlier stages." (PMID 38918775, 2024). "PCGF4/BMI1 has been identified as a tumor suppressor that represses the Ink4a/Arf gene locus directly in collaboration with c-MYC in a transgenic model of a mouse lymphoma." (PMID 39337298, 2024). "In the previous 2017 WHO classification (WHO-HAEM4), these lymphomas, known as DH or triple-hit (TH) lymphomas, were placed in a provisional category of high-grade B-cell lymphomas with MYC and BCL2 and/or BCL6 rearrangements (HGBCL-DH/TH)." (PMID 39684922, 2024). "For instance, venetoclax is an oral BCL-2 inhibitor that was considered a promising addition to R-CHOP, especially in lymphoma patients with MYC and BCL-2 overexpression." (PMID 39596160, 2024). "We used the EμMyc 560 model that recapitulates the immunoglobulin/c-MYC chromosomal translocation observed in aggressive lymphomas such as Burkitt Lymphoma63." (PMID 39438460, 2024). "Physical interaction between PIAS1 SUMO E3 ligase and MYC encouraged its carcinogenic activity in lymphomas." (PMID 38590645, 2024). "According to the findings of other groups, c-MYC expression is inhibited in melanoma, lymphoma and prostate carcinoma cells by diclofenac at concentrations in the range of 0.2 mM to 0.4 mM." (PMID 38229111, 2024). "Contrary to other lymphoma oncogenes, forced expression of MYC is sufficient to generate B-cell neoplasm in mouse model." (PMID 38440231, 2024). "For example, cell lines C8166, HDMYZ and OCIULY19, which are among the most MYC dependent lymphoma lines showed increased dependency compared to A3KAW, SMZ1 and RAJI." (PMID 38326887, 2024). "For example, inactivating the MYC oncogene has been shown to reduce tumor growth in animal models of lymphoma." (PMID 38195537, 2024). "The WHO-HAEM5 specifies that DH lymphomas require MYC and BCL2 rearrangements, called DLBCL or HGBCL with MYC and BCL2 rearrangements because those with BCL6 rearrangement have a diverse gene expression signature." (PMID 40949653, 2024). "Prior studies identified continued MYC-dependence using mouse models of lymphoma and leukemia initiated by MYC51." (PMID 38714690, 2024). "These conclusions are bolstered by the adverse relationship between BMAL1 expression and MYC in a sample of 102 human lymphomas." (PMID 39012661, 2024). "The aberrant expression of MYC drives the uncontrolled growth and rapid proliferation of lymphoma cells, contributing to BL’s aggressive clinical behavior." (PMID 40191738, 2024). "BCL2 rearrangements were detected in 20 of 37 MYC rearranged cases (54%), and these “double-hit” lymphomas are described in the next paragraph." (PMID 38903717, 2024). "Analysis of cfDNA levels across LBCL subtypes showed that they were particularly elevated in patients with high-grade lymphoma with rearrangement of MYC and BCL2 (median 518 ng/mL) in comparison with patients with other LBCL subtypes (p < 0.001)." (PMID 38254810, 2024). "The role of MYC in lymphoma is well established, as MYC overexpression drives B cell proliferation through multiple mechanisms, foremost, the stimulation of the cell cycle." (PMID 39766110, 2024). "One of these near-universal CRMGs contains a rarely studied RBP, RBM42, that interacts with hnRNP K, is a component of stress granules, and is MYC-sensitive in lymphoma cells." (PMID 39464061, 2024).
lymphoma (continued). "Some scholars have found that combined transgenic mice, with T cells or B cells overexpressing MYC and RUNX1 genes, are easily accessible to lymphoma, suggesting that RUNX1 can accelerate MYC-induced lymphoma." (PMID 38172714, 2024). "The final diagnosis for the patient was double hit-lymphoma - high-grade B-cell lymphoma with MYC and BCL-2 rearrangements, a particularly aggressive form of DLBCL with an abysmal prognosis." (PMID 39449881, 2024). "Super-enhancers, including GIMAP, TP73, BCL11b, and MYC enhancers, contribute to inducing leukemia/lymphoma by regulating the expression of TF and cytokines." (PMID 39284807, 2024). "For example, inactivating the MYC oncogene in animal models of lymphoma has been shown to reduce tumor growth." (PMID 38195537, 2024). "Selinexor and eltanexor have also been shown to synergize with the BCL-2 inhibitor venetoclax in double hit lymphoma cell lines and patient-derived xenografts harboring MYC and BCL-2 alterations." (PMID 39749030, 2024). "A double-hit lymphoma is a high-grade B-cell lymphoma (HGBCL) with MYC and BCL2/BCL6 rearrangements." (PMID 39449881, 2024). "These patients have previously been published as part of a prior study (n = 34) investigating MYC, BCL2, and BCL6 rearrangements, pathogenic variants of MYD88 and CD79B, and double-expressor lymphoma." (PMID 38542066, 2024). "This is in line with previously published data describing BCL-XL dependency of MYC-amplified MB in vitro and in vivo, but also in plasma cell neoplasms and lymphoma." (PMID 38184819, 2024). "Using cell numbers as a proxy for disease prognosis resulted in predictions that MYC + BCL2 DH lymphoma would have worse prognosis than MYC + BCL6 DH lymphoma." (PMID 38965209, 2024). "These mice rapidly developed lymphomas, with the presence of both immature and mature B lymphocytes indicating that c-MYC was oncogenic at various stages of B-cell maturation." (PMID 38616733, 2024). "All recipient mice displayed characteristic Eμ-MYC lymphoma pathology, including enlarged lymph nodes, spleen and thymus, elevated white blood cell counts (WBC) and thrombocytopenia." (PMID 36894688, 2023). "In lymphoma, MYC activation occurs through various molecular processes, including mutations, amplification, translocations, altered intracellular localization of the MYC protein, and miRNA-dependent mechanisms." (PMID 36982568, 2023). "The MYC protein promotes cell proliferation, while the antiapoptotic BCL2 protein contributes to accelerating lymphoma progression by interaction with other oncogenes, especially MYC." (PMID 37925380, 2023). "CREBBP mutations have been observed in mice to promote substantial increases in the number of germinal center B cells which promotes development of MYC-driven lymphoma." (PMID 36818048, 2023). "We employed Eμ-MYC/Cas9 doubly transgenic mice and a fetal liver derived HSPC transplantation approach to investigate the tumour suppressive role of TFAP4 during c-MYC-driven lymphoma development." (PMID 36894688, 2023). "We examined the responses of sgTfap4/Eμ-MYC/Cas9 and sgControl/Eμ-MYC/Cas9 lymphoma cell lines to the BH3 mimetic drugs ABT-199/Venetoclax or S63845 that inhibit BCL-2 or MCL-1, respectively." (PMID 36894688, 2023). "This has been successfully performed with the MYC-inhibitor peptide H1 to inhibit MYC transcription at a nanomolar concentration and to induce lymphoma cell killing, suggesting an interesting novel therapeutic principle against lymphoma." (PMID 36969025, 2023). "This study demonstrates the biologic advantage of a selective CDK9 inhibitor for the treatment of MYC+ lymphoma preclinical models which is confirmed by analysis of blood samples from patients treated with 30 mg enitociclib i.v. once weekly." (PMID 37882668, 2023).
lymphoma (continued). "PLK1 has been shown to be a valid target in MYC-driven cells such as lymphoma, glioma, and medulloblastoma, where onvansertib sensitized tumors to radiotherapy, and pediatric malignancies synergizing with vincristine." (PMID 37183219, 2023). "Restricting of dietary serine and glycine can decrease tumor growth in MYC-driven lymphoma animal models." (PMID 36982568, 2023). "We therefore conclude that loss of TFAP4 leads to a block in differentiation during early B cell development, thereby accelerating c-MYC-driven lymphoma development." (PMID 36894688, 2023). "For example, abnormally high levels of c-MYC, as seen in Eμ-Myc lymphoma cells, are known to render cells prone to activating the intrinsic apoptosis pathway." (PMID 36739334, 2023). "In MYC-amplified lymphomas, MCT1 expression was dramatically increased, which indicates MCT1 expression is regulated by MYC." (PMID 37367892, 2023). "The resulting AicdaCre+/ki;R26tdTom+/ki; λ-Myc+/TG mice (hereafter λ-MYC Tom+/ki) allowed genetic tracing of cells that had expressed AID throughout MYC-driven lymphoma generation." (PMID 37809061, 2023). "MYC+ lymphomas are refractory to standard of care and novel treatments that downregulate MYC are needed." (PMID 37882668, 2023). "BCL2 expression is one of the most influential alterations in DLBCL and is already prognostically significant, as DLBCL with MYC and BCL2/BCL6 mutations are termed double hit or triple hit lymphomas and are associated with a worse prognosis." (PMID 36818048, 2023). "Double/triple-hit lymphomas (DHLs/THLs) are an aggressive type of high-grade B-cell lymphomas (HGBLs), characterized by translocations in MYC and BCL2/BCL6." (PMID 37958379, 2023). "Even a partial blockage of KAT6A can help reduce the proliferation of MYC-induced lymphoma and acute myeloid leukemia." (PMID 36770785, 2023). "It is interesting to compare the roles of the different BCL-2 family members in MYC-driven lymphoma development." (PMID 37567974, 2023). "As these DEL classifications do not take DLBCL ITH into account, it was not known if DELs represent two distinct and coexisting clonal phenotypes within a lymphoma—one expressing MYC and the other BCL2." (PMID 37071673, 2023). "CRISPR deletion of TFAP4 in Eμ-MYC transgenic haematopoietic stem and progenitor cells (HSPCs) and transplantation of these manipulated HSPCs into lethally irradiated animals significantly accelerated c-MYC-driven lymphoma development." (PMID 36894688, 2023). "Cyclin-dependent kinase 9 (CDK9) regulates transcriptional elongation and activation of transcription factors, including MYC, making it a potential targeted approach for the treatment of MYC+ lymphomas." (PMID 37882668, 2023). "There were two cases of FL (Cases LYWS-1099 and LYWS-1133), one grade 3A with BCL2 and IRF4 rearrangements, and one transformed FL to high-grade lymphoma that in the transformation acquired MYC and IRF4 rearrangements." (PMID 37555980, 2023). "In Ramos lymphoma cell lines, which are dependent on MYC overexpression, mutations in the HLH motif greatly reduce MYC expression, impede proliferation and sensitize cells to anti-cancer compounds." (PMID 37768948, 2023). "In addition, the experiments with lymphoma-prone transgenic mouse models showed that malignant B cells with a c-MYC activation are highly sensitive to loss to DDX3, suggesting a synthetic lethality between gain of MYC and loss of DDX3 function that could be exploited by small molecule inhibitors." (PMID 37035206, 2023). "So-called double-hit lymphomas usually carry BCL2 and MYC rearrangements, while triple-hit lymphomas additionally bear BCL6-fusions." (PMID 37371852, 2023). "Taken together, these results indicate that Ly27805-Luc is an aggressive MYC-driven lymphoma model with very short latency (20 days on average) and high penetrance (100%)." (PMID 37048617, 2023).